CD4 (CD4 molecule)
Diseases named in the same sentence as CD4 in open-access papers (continued):
Sharing a sentence is not in itself a finding about the gene and the disease.
pancreatic cancer (continued). "However, in line with other studies on pancreatic cancer, most CD39+ CD4+ T cells were FOXP3+ CD25+ Tregs and were not correlated with better survival." (PMID 38335302, 2024). "Previous studies have shown that CD4+ CD39+ T cells and CD8+ T cells double positive (DP) for CD39 and CD103 contain a high frequency of tumor-reactive T cells, but these subsets of T cells have not yet been studied in pancreatic cancer." (PMID 38335302, 2024). "The lack of CD4+ T cells, CD8+ T cells, and NK cells that results in decreased tumor cell clearance is responsible for ubiquitination-related unsatisfactory prognosis in pancreatic cancer patients." (PMID 37540295, 2023). "Additionally, gemcitabine treatment in pancreas cancer patients showed no significant changes in proportions of T and B-cells including CD86 and CD80 APCs or CD4+, CD25+ T-cells." (PMID 25889536, 2015).
Granuloma (247 papers, 2007 to 2025). A compact, organized collection of mature mononuclear phagocytes, which may be but is not necessarily accompanied by accessory features such as necrosis. "In tuberculous granulomas from humans, granuloma associated TLSs are composed of B cells and mycobacteria containing antigen presenting cells surrounded by CD4 + and CD8 + T cells." (PMID 40468399, 2025). "Germinal centers, a scattered distribution of granuloma associated CD4+ T-cells, higher CD8+ T-cell density inside the necrosis and foamy epitheloid cells were associated with a favorable outcome." (PMID 40661952, 2025). "The necrosis of blood vessel walls is driven by inflammatory cytokines and other mediators induced by ANCAs, as well as heightened T-cell activity, especially involving CD4+ T-cells, which is associated with granuloma formation." (PMID 39640133, 2024). "We and others have shown that the induction of IDO expression in granulomas from patients with TB associates with HLA-DR downregulation, which is consistent with immune evasion that disables antigen presentation to CD4+ T cells." (PMID 39114981, 2024). "Currently, the role of T-cells in egg granulomas and fibrosis caused by schistosome infection is mainly focused on CD4+ Th cells, and little is known about the role of CD8 T-cells." (PMID 39590301, 2024). "Single-cell transcriptomic signatures of different granulomas from the same individual lung sample revealed that healing or sterile granuloma were associated with IFN-γ/IL17 producing Th1 CD4+ T-cells." (PMID 37638020, 2023). "Higher frequencies of Mtb-specific CD4+ T cells with balanced Th1/Th17 and IL-10 responses are associated with lower bacterial burden in individual granulomas." (PMID 32793199, 2020). "CD4+ T-cells constituted the main lymphocytic component of the granulomas and were closely associated with the CD68+ macrophages in the central core." (PMID 18477401, 2008). "The accumulation of immature LC in LCH granulomas was associated with the expansion of FoxP3+ CD25 + CD4+ regulatory T cells both in granuloma and in the blood of patients." (PMID 18810271, 2008). "This enabled us to identify several specific histopathological features, including maintained lymphoid structures, distribution patterns of granuloma associated CD4+ and CD8+ T-cells and foamy epitheloid cells to be indicative for a balanced immune reaction and an uncomplicated disease course." (PMID 40661952, 2025). "The depletion of CD4+ cells is associated with the formation of smaller granulomas, but could exacerbate disease severity." (PMID 39466851, 2024). "Therefore, the peripheral blood CD4+ T cell count was associated with the integrity of granulomas, which was also confirmed in the initial logistic analysis of clinical data in this study." (PMID 39205309, 2024). "Such an increase in CD4+ cells in the lungs may have caused the elevated formation of mature granulomas during the chronic stage of infection in both the RD-fed and MFD-fed infected mice." (PMID 36676177, 2023). "Similarly, guinea pigs fed a protein-deficient diet had poorly formed granulomas and marked reductions in CD4 and CD4 lymphocytes in the blood and spleen." (PMID 36248906, 2022). "This could be explained by the persistence of immune cells such as CD4 Th1 or Th17 (due to their greater resistance to apoptosis conferred by the polymorphism), resulting in continued inflammation and persistence of granuloma." (PMID 36543347, 2022). "As HIV infection progresses, severe depletion of peripheral CD4 T cells correlates with increased Mtb presence within granulomas of HIV/Mtb co-infected individuals and loss of interstitial CD4 T cells with an increase in Mtb growth in co-infected humanized mice." (PMID 32730321, 2020).
Granuloma (continued). "At day 30 post-infection, however, CD4+ T cell-specific IL-4Rα deficient mice and wild-type controls showed evidence of granuloma maturation, as defined by an increased number of mature and sterile granulomas, compared with global IL-4Rα−/− mice." (PMID 31475014, 2019). "C3HeB/FeJ mice were infected with MAC and demonstrated a progressive lung infection resulting in an increase in bacterial burden peaking around day 40, developed micronecrosis in granulomas and was associated with increased influx of CD4+ Th1, Th17, and Treg lymphocytes into the lungs." (PMID 31001241, 2019). "Studies in schistosomiasis-associated granulomas demonstrated a role for regulatory CTLA-4+ CD25- CD4+ T cells in protection against host mediated pathology, with blocking of these Tregs resulting in significant weight loss but enhanced recruitment of effector T cells to hepatic granulomas." (PMID 23423646, 2013). "The granuloma associated CD4+ Th2 lymphocytes also proliferated less when restimulated in vitro." (PMID 18369473, 2008). "We have previously demonstrated that the granulomas of M. tuberculosis–infected asymptomatic controllers is characterized by the presence of inducible bronchus associated lymphoid tissue (iBALT), which plays an important role in the induction of protective CD4+ T cell responses." (PMID 39114981, 2024). "Similarly, an eventual reduced ability to mount a CD4+ T-cell response is associated with the reduced maintenance of the granuloma structure and, importantly, a reduced ability to prevent metastasis of infection, similar to innate phase granuloma." (PMID 37110276, 2023). "Furthermore, we investigated the function of Mtb-specific CD4 T cells in lung lesions by using transcription factors and activation markers, and we demonstrated an association between Mtb-specific CD4 T cells expressing T-bet or RORγT and a reduction in the bacterial burden within granulomas." (PMID 37039646, 2023). "Thus, the bacterial burden may drive increased numbers of Mtb-specific CD4 T cells in granulomas, but only polarized Mtb-specific CD4 T cells are associated with a reduced bacterial burden." (PMID 37039646, 2023). "By 8 wk after infection, granulomas increased in all animals in the unvaccinated group and in a subset of animals in the CD4- and CD8α-depleted groups." (PMID 39912921, 2025). "The spleen was observed to have the ability to limit the formation of CD4+ T cell-mediated granulomas." (PMID 40059230, 2025). "Most granulomas in CD4-depleted animals contained higher bacterial burden than those from undepleted animals, implicating CD4 T cells in limiting bacterial growth within granulomas." (PMID 39912921, 2025). "While CD4 + T cells are essential in control of M. bovis infection, the fact that M. bovis persists in most infected cattle and that sterile granulomas are uncommon, demonstrates that in many cases these responses are insufficient to clear the infection." (PMID 40468399, 2025). "The overall reduction in CD4+ T-lymphocytes, together with the entrance of HIV-infected CD4+ T-lymphocytes in granulomas, constitutes a primary factor contributing to the disorganization of the granuloma." (PMID 40431213, 2025). "We diagnosed our patient with CS based on the pathological findings of extensive fibrosis and granulomas, as well as the immunohistochemistry findings of CD4-positive lymphocyte predominance and localisation of CD4 and CD8 lymphocytes." (PMID 40226537, 2025). "Specifically, we represent three types of macrophages (resting, infected, and activated), two types of Mtb (intracellular and extracellular), and two subsets of effector T cells (CD4 + and CD8+), hereafter referred to as granuloma-associated T cells." (PMID 40334195, 2025). "The histological results showed lymphoid cells and small epithelioid granulomas, while bronchoalveolar lavage revealed lymphocytosis, with a significantly elevated CD4+/CD8+ ratio." (PMID 39867510, 2025).
Granuloma (continued). "Within granulomas, CD4+T cells, particularly Th1, Th17, and Th17.1 subsets, are oligoclonally expanded and exhibit a phenotype consistent with chronic antigenic stimulation and partial exhaustion, driving ongoing inflammation." (PMID 41197661, 2025). "In an MTB infection, bLf demonstrated its ability to increase the number of CD4+ Th1 cytokine-producing cells in the lung, thereby promoting the amelioration of pathological response and preventing the formation of granuloma." (PMID 41155294, 2025). "Although macrophages are at the granulomatous core, surrounded and supported by recruited CD4+T cells and monocyte precursors, multiple other immune and structural cell types are present within granulomas and affected tissues." (PMID 41197661, 2025). "On the other hand, granulomas can also provide a protective niche by restricting CD4+ T cells away from the core and inhibiting Th1 cells through IL-10 mediated suppression." (PMID 39861915, 2025). "Granuloma-associated CD4 + and CD8 + T cells are recruited to a developing granuloma and proliferate based on infected and activated macrophage cell counts that represent a proxy for cytokine signaling produced by each cell, respectively." (PMID 40334195, 2025). "Granuloma formation occurs through activation of CD4-positive T cells and macrophages against unidentified antigens, resulting in the release of cytokines such as interleukin-2, interferon-γ, and tumour-necrosis-factor-α." (PMID 41541976, 2025). "It inhibits macrophage apoptosis, depletes CD4+ T lymphocytes, which impacts the functional structure of granulomas, and elicits other intricate immune responses." (PMID 41476888, 2025). "CD4+ T lymphocytes are distributed within the granulomas, whereas CD8+ T lymphocytes are distributed at the margin of the granulomas." (PMID 41393126, 2025). "Lymphocytic infiltration in the vicinity of the granulomas with CD4+ and CD8+ cells, including a predominance of CD4+ cells, was observed (mean lymphocyte count of 42/HPF)." (PMID 40928208, 2025). "Results showed that CD4+ and CD8+ T cells were gathered around all granuloma types in biopsy specimens, but limited CD4+ and CD8+ T cells were found in the post-mortem tissues." (PMID 38361935, 2024). "Previous studies have found that T lymphocytes and CD4+ Th cells play a critical role in granuloma formation." (PMID 38361935, 2024). "Due to the crucial role that CD4+ T cells play in the formation of TB granulomas, the ability of B cells to induce or block this pathway illustrates their importance in granuloma formation." (PMID 39717773, 2024). "We observed similar frequencies of CD4+ T cells but significantly higher frequencies of CD8+ T cells in the granulomas of D1MT+cART-treated as compared with cART-only–treated RMs." (PMID 39114981, 2024). "Frequencies of Tregs, characterized by CD4 expression and immuno-modulatory molecules, were elevated among IgG granulomas compared with naive lesions." (PMID 39214090, 2024). "For individuals with HIV who experience CD4+ T-cell depletion and thus alterations in their immune response, the formation of granulomas is of particular interest." (PMID 39066368, 2024). "Given that HIV infection can cause the destruction of CD4+ T lymphocytes, we conducted a statistical analysis of the absolute values of peripheral blood CD4+ T lymphocytes in both groups to investigate whether these values are correlated with the degree of granuloma completeness." (PMID 39205309, 2024). "Using Kendall’s tau-b correlation analysis to further explore the relationship between granuloma formation and peripheral blood CD4+ T lymphocyte count, a correlation coefficient of 0.49 was obtained, with p = 0.001." (PMID 39205309, 2024). "Deletion experiments in the in vitro model of human granuloma have suggested that CD4 T-cells constitute the only T-cell population critical for granuloma formation." (PMID 38392836, 2024).
Granuloma (continued). "This clinical observation mirrors preclinical in vivo data of a mouse model of granulomatosis in which CD4+ T-cell-depleted humanized mice were unable to form granulomas upon mycobacterial infection." (PMID 38521838, 2024). "IL-17 has an established role in recruitment of CD4+ T cells to the lung following vaccination and promotion of granuloma development." (PMID 38390338, 2024). "Some studies have shown that a reduction in peripheral blood CD4+ T lymphocyte levels leads to decreased granuloma integrity." (PMID 39205309, 2024). "Through HE staining, pathological analysis, and immunohistochemical analysis, we found that the count of CD4+ T cells in tissues linearly correlates with the integrity of granulomas." (PMID 39205309, 2024). "Through statistical analysis of peripheral blood CD4+ T cell counts, tissue CD4+ T cell proportion, and the integrity of granulomas, it was observed that HIV infection leads to poor formation of tuberculous granulomas." (PMID 39205309, 2024). "A rank-sum test showed a statistically significant correlation between peripheral blood CD4+ T cell count and the formation and tendency of granulomas (p = 0.0018)." (PMID 39205309, 2024). "The T lymphocytes and CD4-positive helper T (Th) cells play a key role in granuloma formation in TBM patient, and the interactions between CD4+ Th cells and T lymphocytes induce the IFN-γ production and then activate the macrophages to engulf and digest M.tb." (PMID 38361935, 2024). "In summary, we provided an in-depth characterization of primary infection, reinfection, and CD4+ T cell-depleted reinfection macaque granulomas, identifying potential mechanisms by which CD4+ T cells contribute to anti-mycobacterial immunity." (PMID 39214090, 2024). "IgG granulomas had lower frequencies of neutrophils relative to naive granulomas, and depletion of CD4+ T cells led to increased frequencies of neutrophils." (PMID 39214090, 2024). "In contrast, we histologically observed that granulomas with high CD4 T cell frequencies and lower Mtb replication rates contained more epithelioid macrophage populations." (PMID 39253081, 2024). "More recently, our group have used a number of cell markers (CD3, CD4, Iba1, myeloperoxidase, Mac387) to describe presence and frequency of inflammatory and immune cells in granulomas up to 27 wpc." (PMID 37901102, 2023). "The central part of a granuloma is composed of macrophages, modified macrophages, epithelioid cells, and giant cells, with CD4+ T-lymphocytes between them." (PMID 37109576, 2023). "Macrophages, modified macrophages, epithelioid, and giant cells with CD4+ T cells are located in the central part of the granuloma, while CD8+ T cells, fibroblasts, macrophages, and fibrocytes are in the peripheral part of the granuloma." (PMID 37189479, 2023). "Comparing the frequencies of tetramer+ cells in uninvolved lungs or in the periphery with the frequencies observed in lung granulomas revealed that the granulomas are enriched for Mtb-specific (tetramer+) CD4 T cells." (PMID 37039646, 2023). "Rv1196371-385 tetramer+ cells and CFP-10 tetramer+ CD4 T cells in granulomas had significantly higher frequencies of T-bet and RORγT expression, compared to tetramer− cells." (PMID 37039646, 2023). "M. bovis-induced granulomas in cattle are characterized by a strong expansion of IFN-γ-producing CD4+ T-cells and M. bovis-specific B lymphocytes." (PMID 37638020, 2023). "In summary, our data demonstrate that granulomas are enriched sites for Mtb-specific CD4 T cells, compared to lung tissue, LNs, or blood." (PMID 37039646, 2023). "There were no significant changes between the BCG- or recombinant BCG-vaccinated groups in terms of the number of CD4+ T cells, which are considered essential for the maintenance of granulomas." (PMID 36232295, 2022).